EP300 (EP300 lysine acetyltransferase)
Diseases named in the same sentence as EP300 in open-access papers (continued):
Sharing a sentence is not in itself a finding about the gene and the disease.
CNS tumors (6 papers, 2020 to 2025). "Two CNS tumors with fusions between CREBBP, or its paralog EP300, and BCORL1, and approximately twenty CNS tumors with CREBBP/EP300::BCOR fusions have been reported to date." (PMID 38216991, 2024). "The core characteristic of “CNS tumor with BCOR/BCOR(L1)-fusion” is defined as predominant presence of a BCOR fusion with often EP300 as the fusion partner and/or characteristic CNV." (PMID 38637838, 2024). "In a single case, PLAGL1 was fused to EP300, a fusion partner known from ‘CNS tumors with BCOR alteration’." (PMID 34355256, 2021). "After the first description of CNS tumor with BCOR ITD, other tumors with overlapping morphological and immunohistochemical features, but harboring fusions of BCOR with either EP300 or its paralog CREBBP, instead of BCOR ITD, have been reported in the CNS." (PMID 38216991, 2024). "CNS tumors with BCOR/BCOR(L1) fusion are characterized by the presence of a BCOR fusion, often paired with EP300 as the typical fusion partner, with or without hallmark CNV within chromosomes 22q12.31 and Xp11.4." (PMID 40724977, 2025). "In conclusion, we present two novel cases of the rare CNS tumor having an EP300::BCOR fusion in adults, representing a distinct subtype not yet included in the WHO classification." (PMID 36782314, 2023). "In an additional 686 primary CNS tumor cases of adult and pediatric patients, assessed via FISH or RNA-seq analysis, we identified an additional case demonstrating a BCOR fusion to a paralog of CREBBP, namely EP300, similar to that seen in a recently reported series." (PMID 32493417, 2020).
adenocarcinoma (4 papers, 2016 to 2023). A common cancer characterized by the presence of malignant glandular cells. "The KMT2D, GNAS, EP300, GRM3, and PIK3CG mutations were all significantly higher in patients with squamous than those with adenocarcinoma (P = 0.0066, P = 0.019, P = 0.0075, P = 0.017, and P = 0.0075, respectively)." (PMID 37301854, 2023).
cardiac disease (4 papers, 2014 to 2020). "While deficiency or deregulation of Ep300 gene is associated with defective cardiogenesis, p300 abnormality in adults is associated with cardiac disease development." (PMID 32765954, 2020).
gastrointestinal tumors (3 papers, 2025). "While no literature supports GH therapy for RSTS, studies suggest a link between EP300 mutations and gastrointestinal tumors." (PMID 40672389, 2025).
genetic disorder (3 papers, 2020 to 2025). "We used SIPS agents and validated the role of p300 in lymphoblastoid cell lines (LCLs) derived from patients affected by a rare genetic disorder with pathogenetic variants in EP300, the gene coding for p300, and healthy donors (HD)." (PMID 40640194, 2025). "A genetic disorder, Rubinstein–Taybi syndrome, is associated with mutations in p300 (also known as EP300), which is characterized in part by hypoplasia of the corpus collosum and congenital hypomyelination." (PMID 32089836, 2020).
retinopathy (3 papers, 2016 to 2023). "To examine the role of EP300 directly, we developed a larval zebrafish model of light-induced retinopathy." (PMID 27242532, 2016). "To examine the function of EP300 in light-induced retinopathy, we developed a novel model using larval zebrafish." (PMID 27242532, 2016). "Taken together with these reports, our findings support a role for EP300 as a key modulator of the anti-apoptotic effects of the endogenously activated STAT1/3–IL6ST/OSMR axis in light-induced retinopathy." (PMID 27242532, 2016). "In this study, we demonstrated that inhibition of EP300 by C646 significantly increased (i) retinal apoptosis, (ii) photoreceptor damage, and (iii) proliferation of putative Müller cells in a larval zebrafish model of light-induced retinopathy." (PMID 27242532, 2016). "To further investigate the role of EP300 in retinal protection, we performed whole-mount immunohistochemical staining of larval zebrafish with light-induced retinopathy using anti-Zpr3 antibody, which detects both rod and cone photoreceptor cell outer segments." (PMID 27242532, 2016). "Moreover, the interaction between EP300 and STAT3 is increased by treatment with CNTF or FGF2, suggesting a possible mechanism whereby CNTF and FGF2 reduce apoptosis and protect photoreceptor cells from light-induced retinopathy." (PMID 27242532, 2016).
autosomal dominant disease (1 paper, 2010). Autosomal dominant form of disease. "Peak heights were normalized against 3 reference probes (EXT1, CREBBP and EP300), selected from known autosomal dominant disease genes, which would not be deleted or duplicated without an obvious phenotype." (PMID 20957197, 2010).
head and neck tumors (1 paper, 2014). "Another PMT, MLL2, and the HAT EP300 are found mutated in 18% and 7.8% of head and neck tumors, respectively." (PMID 25484917, 2014).
EP300 also shares sentences with these, for which no sentence is quoted: osteosarcoma (17 papers); neurodegenerative disease (13); metabolic disease (10); non-small cell lung carcinoma (10); Anxiety (8); Hypertension (8); type 2 diabetes (8); cardiovascular diseases (7); neurodevelopmental disorder (7); renal fibrosis (7); autoimmune disease (6); head and neck squamous cell carcinoma (6); ischemic stroke (6); prostate tumors (6); Cerebral ischemia (5); breast (4); clear cell renal carcinoma (4); diabetic nephropathy (4); diabetic retinopathy (4); Glucose intolerance (4); idiopathic pulmonary fibrosis (4); ischemia (4); liver diseases (4); neurological disorders (4); T-cell leukemia (4); -Taybi syndrome (3); acute kidney injury (3); anemia (3); cutaneous squamous cell carcinoma (3); developmental delay (3).
A further 210 diseases each share a sentence with EP300 in 3 papers or fewer.